AFP (alpha fetoprotein)
Diseases named in the same sentence as AFP in open-access papers (continued):
Sharing a sentence is not in itself a finding about the gene and the disease.
tumor (continued). "However, the up-regulation of DLGAP5 positively correlated (P<0.05) with the level of alpha-fetoprotein (AFP) (P=0.036), the presence of portal vein tumor thrombus (PVTT) (P=0.015) and postoperative recurrence (χ2=4.255, P=0.039)." (PMID 24324629, 2013). "Tumor multiplicity was only associated with OS, while AFP and tumor encapsulation can predict TTR, not OS." (PMID 23601182, 2013). "If the AFP is normal, the tumor is probably benign, as in cases of teratoma and epidermoid cyst." (PMID 24400293, 2013). "Hence we conclude that with hCMV/AFP driven transgene expression a considerable tumor specificity accompanied by strong activity in the target tissue (HCC) can be achieved." (PMID 23734827, 2013). "According to Japanese national data, in addition to the MC, it is reported that the values of tumor markers [α-fetoprotein (AFP) and DCP] define prognosis, but as various factors are involved in tumor markers, it is difficult to incorporate them into international eligibility criteria of LT for HCC." (PMID 23863893, 2013). "It correlates positively with AFP, tumor size and staging, MELD score and Child-Pugh score." (PMID 23518665, 2013). "AFP is the most useful tumor marker for HCC and is produced by immature cells of the fetus." (PMID 23717429, 2013). "α-Fetoprotein (AFP), initially identified from human fetal tissue, is normally produced in some fetal organs, proliferating hepatocytes and some adult cancer cells, including hepatocellular carcinoma cells and yolk sac tumor cells." (PMID 24083471, 2013). "Univariate analysis revealed that age >47 years old, tumor size >3 cm, alpha-fetoprotein >8 ng/mL, albumin ≤4 g/dL, AST >42 U/L, ALT >50 U/L, AST/ALT >0.89, presence of occult HBVCI, and absence of overt HBVCI were associated with a shorter disease-free survival." (PMID 23805180, 2013). "It is worth noting that 5-hmC was associated with tumour size [OR 0.847, 95% CI (0.746–0.962), P = 0.011] and that HCC patients with a tumour size ≥5.0 cm showed a lower 5-hmC content and higher levels of serum AST, ALT/AST, GGT and AFP." (PMID 24143196, 2013). "AFP has been used for many years as a convenient biomarker for HCC because of its associations with liver carcinogenesis and was recently recognized as linked with aggressive tumor behavior." (PMID 23977041, 2013). "Age, AFP level, tumor size, ascites, and tumor thrombus may be useful prognostic indicators in HCC patients." (PMID 23552472, 2013). "The relationship between AFP levels and tumor burden has been determined in HCC patients." (PMID 24455285, 2013). "In regard to tumor factors, several studies have reported that more young than old patients have high AFP levels, that is, the rates of cases in which AFP is equal to or exceeds a value of 400 ng/ml range from 52.6 to 82.0%, and rates for an AFP of ≥10,000 ng/ml range from 31.6 to 60.0%." (PMID 23452898, 2013). "Since the 1970s, AFP has been used as a tumor marker for the diagnosis of HCC." (PMID 23981851, 2013). "Regarding tumor markers, the total inhibin level was 1,069 U/L (normal <100 U/L for prepubertal child) and the alpha fetoprotein levelwas 987 μg/L (normal 1 to 200 μg/L) while B human chorionic gonadotropin, lactic dehydrogenase and alkaline phosphatase were negative." (PMID 22734844, 2012). "For better understanding the potential role of miR-182 in HCC progression, we analyzed its correlation with some clinicopathological variables including age, sex, HBV infection, AFP, tumor number, tumor size, expression of MTSS1, histological grade, portal vein invasion and recurrent time." (PMID 22681717, 2012). "Furthermore, low expression of SIRT3 was significantly correlated to differentiation (P = 0.013), clinical stage (P = 0.005), serum AFP level (P<0.01), tumor multiplicity (P = 0.026) and relapse (P = 0.028)." (PMID 23272146, 2012).
tumor (continued). "However, the expression did not correlate with some other clinical observations, such as the size of tumor, metastasis, cancer embolus and AFP concentration." (PMID 22540002, 2012). "Because a single biomarker will not provide information regarding both tissue type and malignant transformation throughout the various stages of tumor development and progression, we further combined tissue hnRNP K intensity and serum AFP concentration to form a biomarker panel." (PMID 22760167, 2012). "Low OCT1 (SLC22A1) mRNA expression levels were associated with advanced HCC stages as indicated by a higher frequency of T3 carcinomas (p = 0.025) with a larger tumor diameter (p = 0.035), a worse tissue differentiation as indicated by grading (p = 0.001) and higher AFP-levels (p = 0.019)." (PMID 22439694, 2012). "The relevance of AFP mRNA as a marker of circulating tumor cells is better but is also controversial because these cells have not been further characterized, and it has been shown that they may correspond to normal circulating hepatocytes." (PMID 22690340, 2012). "However, in multivariate analysis only aP, bilirubin, ascites, AFP, number of tumor nodes and BCLC-tumor extension remained strong predictors of survival." (PMID 23071507, 2012). "Additionally, inhibition of tumor growth was observed significantly in mice following vaccination with AFP/IL-2-DC compared with mice vaccinated with other vaccines (P<0.01)." (PMID 23170121, 2012). "Moreover, serum levels of the tumor markers alpha-fetoprotein, protein induced by vitamin K absence or antagonist II, carcinoembryonic antigen, and carbohydrate antigen 19-9 were normal." (PMID 23320180, 2012). "AFP is currently widely recognized as a tumor-related prognosis antigen for HCC." (PMID 23210562, 2012). "Higher ephrinA5S expression in peritumoral liver tissue, positive HBsAg and higher Alb showed a reduced lethal risk to 0.42×, 0.39× and 0.40×, respectively, whereas, elder age, larger tumor size and higher AFP exhibited 1.44×, 1.75× and 2.37× poor disease-free survival risk, respectively." (PMID 22860012, 2012). "However, it does not include important prognostic parameters such as the unifocal, multifocal, or diffuse state of the tumor, existence of a portal vein thrombosis or distant metastasis and the alpha-fetoprotein (AFP) rate." (PMID 22655206, 2012). "Decrease of SIRT3 in HCC was significantly correlated with clinical stage, serum AFP level, tumor differentiation and tumor multiplicity, indicating that SIRT3 might be involved in HCC progression." (PMID 23272146, 2012). "Serum YKL-40 was associated with age (P = 0.013) and serum AFP (P = 0.020), but not with the other characteristics such as gender, etiology, Child-Pugh class, tumor size, vein invasion and number of TACE sessions." (PMID 22970277, 2012). "However, the AFP level was proportional to the rate of viable tumour cells, which was only 20% in treated compared to control cultures (determined by counting the live cells with trypan blue staining)." (PMID 22666492, 2012). "Finally, we analyzed the association of gene amplification with clinical characteristics of HCC patients, including age, AFP level, tumor grade, and tumor size." (PMID 22912832, 2012). "Alpha-fetoprotein (AFP) is the most common and classical tumor marker used for HCC evaluation." (PMID 23162601, 2012). "Non-seminoma testis cancer can cause an elevated AFP level in association with elevated levels of other tumor markers such as beta-human chorionic gonadotropin and lactate dehydrogenase." (PMID 22559879, 2012). "Secondly, RFA and alcohol injection are theoretically more likely to be effective when used in patients with early-stage tumors, which are more often observed in SLT recipients who have a lower number of tumors, smaller diameter of the largest tumor, and lower preoperative AFP level." (PMID 22574187, 2012). "After tumor removal, the patient’s high AFP level persisted for 2 years." (PMID 22559879, 2012).
tumor (continued). "Vascular invasion (macroscopic and microscopic) is the strongest predictor of recurrence although other factors such as tumor size, number of nodules, α-fetoprotein (AFP) levels, degree of differentiation, and satellite lesions are also associated with recurrence." (PMID 22682366, 2012). "Hence, alpha-fetoprotein is generally used as a screening tumor marker to compliment ultrasound liver tests for the surveillance of HCC." (PMID 23166534, 2012). "As concerns RASSF2, its downregulation was detected only at tumor stage and was closely associated with elevated serum alpha-fetoprotein level, but not significantly with clinical stage and hepatic fibrosis." (PMID 22548173, 2012). "Most of the tumor cells within tumor nodules stained positively for AFP (68.7±6.21%)." (PMID 22558209, 2012). "Tumor markers including AFP, CEA, and CA19-9 were within normal range in all cases." (PMID 22899877, 2012). "Furthermore, PLK4 expression significantly correlated with clinicopathological parameters, including clinical stage (P = 0.034), serum α-fetoprotein (AFP) (P = 0.019) and tumor size (P = 0.032)." (PMID 22829937, 2012). "The ratio of AFP level to tumor diameter may be a better predictor of recurrence after curative resection than serum AFP level alone." (PMID 22559879, 2012). "HBV-L-AR(−/y) mice that received a low dose of the carcinogen N'-N'-diethylnitrosamine have a lower incidence of HCC and present with smaller tumor sizes, fewer foci formations, and less alpha-fetoprotein HCC marker than do their wild-type HBV-AR(+/y) littermates." (PMID 22647077, 2012). "Serum AFP could be detected before the subcutaneous tumour was apparent and the AFP level increased along with tumour development." (PMID 22666492, 2012). "Scintigraphy with 99mTc-labelled monoclonal anti-AFP is mainly used in the tumor staging." (PMID 21702993, 2011). "However, no such correlation was detected in age, sex, etiology of chronic liver disease, tumor diameter and number, serum AFP, AFP and TUNEL staining (borderline), type or level of SCCA staining." (PMID 22151825, 2011). "Because the serum AFP level decreases in response to effective treatment, measurement of the serum AFP level is carried out during follow-up of patients after treatment or for the detection of tumor recurrence." (PMID 21554678, 2011). "Serum Alpha-fetoprotein and Gaussia luciferase increased 5 weeks after tumor-cell inoculation." (PMID 21853130, 2011). "Previous studies showed that AFP mRNA may be investigated as a surrogate marker for isolated tumor cells (ITC) of HCC, and may predict HCC recurrence after curative hepatectomy." (PMID 22087143, 2011). "However, the specificity and prognostic value of AFP mRNA for circulating HCC tumor cells remains questionable." (PMID 22087143, 2011). "For HCC, early studies have shown that AFP levels decrease rapidly after complete surgical resection and increase with tumor recurrence, suggesting that AFP response could potentially predict tumor response." (PMID 22087135, 2011). "Meanwhile, tumor size, serum AFP, TNM stage, tumor number and vein invasion were all independent prognostic factors for OS; while tumor size, HBsAg positive, TNM stage, tumor number, vein invasion and peritumoral ZBTB20 expression were independent prognostic factors for DFS." (PMID 21702992, 2011). "AFP serves as the most common serum biomarker for HCC and, as it is from undetectable to 10 ng/mL in healthy adults, has also been identified as a specific tumor-associated antigen for HCC immunotherapy." (PMID 21969837, 2011). "We and others have investigated AFP as a tumor rejection antigen for immunotherapy of HCC." (PMID 21969837, 2011). "Thoraco-abdomino-pelvic CT scan and tumor markers (AFP and hCG) were normal." (PMID 21714871, 2011).
tumor (continued). "Serum AFP level is also considered an effective tumor marker in the surveillance of HCC recurrence." (PMID 22087135, 2011). "Together, these findings suggest that the PIVKA-II levels are independently related to extrahepatic metastases regardless of serum AFP level and tumor staging; additionally, they showed a strong association with early stages with low AFP." (PMID 21985636, 2011). "Finally, 15 cases were MCT, with raised AFP in 5 (33%), both tumor makers rose in 4 (26.6%) and normal tumor markers in 6 (40%)." (PMID 29147233, 2011). "Furthermore, the patient's AFP level was closely corelated to tumor metastasis, which was a good indicator for tumor metastasis and made the surgical approach possible." (PMID 22123282, 2011). "Several tumor markers have been proposed as complements or substitutes for AFP in HCC diagnosis." (PMID 21092242, 2010). "Tissue tumour markers: AFP, CEA, HCG can be used for differential diagnosis." (PMID 22933902, 2010). "Therefore, negative staining with OCT-3/4, CD-30 and AFP antibodies as well as normal AFP and CA-125 levels suggested a gestational origin of the tumor." (PMID 21108779, 2010). "Moreover, DCP level was reported to be closely correlated with tumor progression and prognosis, while HCC with high serum levels of DCP and low levels of AFP were an indication of larger tumor size." (PMID 21092242, 2010). "Indeed, the level of AFP-L3 correlated significantly with differentiation and number of HCC although that of AFP was correlated with tumor size and differentiation." (PMID 20482774, 2010). "AFP in preclinical studies is a reliable biomarker of the tumor take rate and growth." (PMID 24281167, 2010). "Tumour markers were within the normal range: alpha- fetoprotein (AFP) (1.46 μg/L; normal range <13.4), carcinoembryonic antigen (CEA) (1.79 μg/L; normal range < 3.4), cancer antigen 19/9 (CA19-9) (16.93 kIU/L; normal range < 37), prostate-specific antigen (PSA) (1.44 μg/L, normal range < 4)." (PMID 22933926, 2010). "Each presumptive diagnosis of the GCTs was made according to the tumor's clinical features, neuroimaging results, serum tumor marker level (alpha fetal protein [AFP], beta human chorionic gonadotropin level [beta-hCG]) and response to radiotherapy and/or chemotherapy." (PMID 20178649, 2010). "In addition, the results showed a correlation between CIMP and Hangzhou criteria, which consider tumor size, histological grading, and serum AFP level." (PMID 20678188, 2010). "Of the tumour markers examined, there was some evidence that AFP above 16 ng ml−1 may be predictive of response (64 vs 25% P=0.02) whereas elevated β-HCG, CA19-9 and CGA were uninformative." (PMID 20234360, 2010). "Where there is concern regarding the patient's performance status or age, as is the situation in this case, an expectant approach is not unreasonable with close clinical surveillance, regular cross-sectional imaging and monitoring of serum tumour markers (AFP, HCG, Ca125 and LDH)." (PMID 19538751, 2009). "Further study included a serum level of alpha-fetoprotein (AFP), which resulted markedly elevated, and a conclusive esophagogastroduodenoscopy describing an elevated tumour growing through the cardia and gastroesophageal junction with foci of necrosis and haemorrhage." (PMID 19674468, 2009). "Diagnostic studies include serum tumor markers (negative alpha fetoprotein, beta HCG, LDH) ultrasonography (hypoechoic and homogenous appearance) and frozen section." (PMID 21151545, 2009). "Age, AFP, γ-GT, tumor size, number, vascular invasion and encapsulation were predictors for DFS." (PMID 19948069, 2009). "Some tumor markers, such as human cervical cancer oncogene and human telomerase reverse transcriptase mRNA, have also been indicated to have higher accuracies than AFP." (PMID 27942274, 2009). "In addition, tumour factors such as tumour size (>3 cm), tumour number (multiple), AFP (>400 ng ml−1), and PVTT were also independent prognostic factors." (PMID 18349849, 2008).
tumor (continued). "However, the tumor markers alpha-fetoprotein (AFP) and Human Chorionic Gonadotropin beta (HCG beta) were within the physiological range." (PMID 20177483, 2008). "Moreover, tumor cells also secrete molecules such as AFP and MUC1, all of which affect the maturation and function of DCs." (PMID 18793383, 2008). "In our study, all AFP-producing tumours intensely expressed MAGE-A10 mRNA in the primary lesions." (PMID 18594524, 2008). "However, greater than 70% of HCC patients have a high serum concentration of AFP because of the tumor excretion." (PMID 17244360, 2007). "Tumor production of AFP was confirmed by immunohistochemical staining." (PMID 17634124, 2007). "Moreover, serum IGF-II level seems to be an independent serologic marker or a complementary tumor marker to AFP for diagnosis of small HCC." (PMID 17244360, 2007). "Therefore, it is reasonable to postulate that the escaping of tumor cells from immune surveillance is partly attributable to the apoptosis of lymphocytes induced by AFP." (PMID 16080799, 2005). "Experimental results obtained from the present study showed that AFP was capable of suppressing the growth of Jurkat cells with the concomitant proliferation of Bel 7402, indicating the diversity effects of AFP on the regulation of immune and tumor cells growth." (PMID 16080799, 2005). "During the last decade, it has been confirmed from a multitude of studies that AFP as a growth regulator modulates the ontogenic growth and tumor progression even though the overall findings remain controversial and their interpretations are still being debated." (PMID 16080799, 2005). "The hepatocytic nature of the cHCC cell line is further indicated by the activity of the liver-specific enzyme ALT and the expression of hepatocyte markers, like serum albumin, ceruloplasmin, and alpha-fetoprotein, as it is also the case for the human tumor liver cell line HepG2." (PMID 15566568, 2004). "PIVKAII and GGTII are useful tumour markers complementary to AFP for diagnosis of HCC." (PMID 12799630, 2003). "In only two cases was there ultrasound evidence of tumour development at the time AFP was first found to be elevated; in the remainder a diagnosis of HCC, based on ultrasound screening, was established at a median time of 3.6 months (range 1-18 months) after entry into the study." (PMID 9010032, 1997). "Multivariate analysis showed that the tumor marker AFP was not an independent risk factor." (PMID 40936688, 2025). "Four years post operation, she was again diagnosed with three HCC tumor recurrences seen on CT scan (unidimensional at 5.4 cm, 3.7 cm, and <1.0 cm at segments 4-5, segment 5, and segment 7, respectively), with concurrent serum alpha-fetoprotein (AFP) level of 45,598 ng/mL." (PMID 40726876, 2025). "Furthermore, the transformation of liver injury to HCC in our investigation was demonstrated by increased tumor markers (AFP, AFU, CEA, TGF-β1, YAP, TAZ, and HIF-1α) and a histological analysis of the liver that showed an increase in the size and quantity of tumor nodules in the HCC group." (PMID 40439888, 2025). "However, tumor markers commonly associated with liver malignancies (AFP, CA 19-9, and CEA) were negative, prompting further investigation." (PMID 39902020, 2025). "Furthermore, we compared these findings with the tumor markers AFP and DCP." (PMID 40940925, 2025). "In addition, AFP has been widely used to monitor the progression of the disease, with elevated concentrations correlating with greater tumor burden, more advanced disease stages, and higher biological aggressiveness, potentially reducing immunotherapy effectiveness and worsening patient prognosis." (PMID 41137952, 2025).